GUCY1B1 (guanylate cyclase 1 soluble subunit beta 1)
Description:
Mediates responses to nitric oxide (NO) by catalyzing the biosynthesis of the signaling molecule cGMP.
Synonyms: GUC1B3; GUCSB3; GUCY1B3; GC-SB3; GC-S-beta-1; GUCB3
Tractability: Small molecule: an approved drug acts on it; a structure with a bound ligand is known; a high-quality ligand is known; it has a high-quality binding pocket; it belongs to a druggable protein family. PROTAC: ubiquitination databases record sites on it; a small molecule that binds it is known.
Gene: Protein-coding gene on chromosome 4 (155,758,988 to 155,807,811, forward strand). Ensembl gene ENSG00000061918.
Subcellular location: Cytoplasm
Subcellular location (Human Protein Atlas): Cytosol
Pathways (Reactome):
Hemostasis: Nitric oxide stimulates guanylate cyclase
Muscle contraction: Smooth Muscle Contraction
Gene Ontology:
Molecular function: guanylate cyclase activity; protein binding; heme binding; adenylate cyclase activity; cytidylate cyclase activity; Hsp90 protein binding; nitric oxide binding; phosphorus-oxygen lyase activity; protein-containing complex binding
Biological process: cGMP biosynthetic process; nitric oxide-cGMP-mediated signaling; cellular response to nitric oxide; response to oxygen levels; cyclic nucleotide biosynthetic process; intracellular signal transduction
Cellular component: guanylate cyclase complex, soluble; cytoplasm; cytosol; glutamatergic synapse; presynaptic active zone cytoplasmic component; protein-containing complex
Genetic constraint (gnomAD): Loss-of-function variants: 9 observed, 19.69 expected, observed/expected ratio (o/e) 0.46, 90% interval 0.28 to 0.8. The upper end of that interval is the gene's LOEUF score, 0.8, which puts it in group 3 of 6, group 1 being the genes least tolerant of losing a copy. Missense variants: 170 observed, 267.64 expected, observed/expected ratio (o/e) 0.64, 90% interval 0.56 to 0.72. Synonymous variants: 100 observed, 95.25 expected, observed/expected ratio (o/e) 1.05, 90% interval 0.89 to 1.24.
Homologues: Orthologues: macaque GUCY1B1 (100% identical), chimpanzee GUCY1B1 (99% identical), dog GUCY1B1 (99% identical), mouse Gucy1b1 (99% identical), guinea pig GUCY1B1 (99% identical), rat Gucy1b1 (99% identical), pig GUCY1B1 (98% identical), tropical clawed frog gucy1b1 (94% identical), rabbit GUCY1B1 (93% identical), zebrafish gucy1b1 (87% identical), Drosophila melanogaster Gycbeta100B (59% identical). Paralogues in human: GUCY1A2 (36% identical), GUCY1A1 (33% identical), NPR1 (26% identical), NPR2 (26% identical), GUCY2F (26% identical), GUCY2D (25% identical), GUCY2C (21% identical), ADCY8 (17% identical), ADCY2 (17% identical), ADCY6 (17% identical), ADCY7 (17% identical), ADCY1 (16% identical), and 5 more.
Diseases named in the same sentence as GUCY1B1 in open-access papers:
GUCY1B1 is named in the same sentence as 10 diseases in open-access papers, as found by Europe PMC text mining. Sharing a sentence is not in itself a finding about the gene and the disease. The quoted sentences say what the papers report.
hypertrophic cardiomyopathy (1 paper, 2025). A condition in which the myocardium is hypertrophied without an obvious cause. "We also observed enrichment in pathways associated with circadian entrainment (e.g., GNG11, GUCY1B1) and hypertrophic cardiomyopathy (e.g., ITGB3, ITGA2B, IL6), suggesting systemic disruptions in PitNET PBMCs." (PMID 41253784, 2025).
tumor (4 papers, 2011 to 2023). "Lower GUCY1B1 protein expression in sgB1-2 tumours compared to control sgNTA tumours at the conclusion of the study was confirmed by IHC and western blot of tumour lysates." (PMID 34789728, 2021). "Furthermore, our data suggest a role of GUCY1B1 in tumour initiation, since CDX17P sgB1-2 tumours took significantly longer to reach the specified randomization volume compared to CDX17P sgNTA tumours." (PMID 34789728, 2021).
GUCY1B1 also shares sentences with these, for which no sentence is quoted: atherosclerosis (2 papers); astrocytomas (1); cancer (1); glioblastoma (1); glioma (1); Hypertension (1); preeclampsia (1); pulmonary hypertension (1).